ATF4 (activating transcription factor 4)
Diseases named in the same sentence as ATF4 in open-access papers (continued):
Sharing a sentence is not in itself a finding about the gene and the disease.
glioma (continued). "In agreement, THC induced an ER-stress response in human and mouse glioma cells that promoted autophagy and apoptosis via TRIB3, inducing expression of ATF4, CHOP, and TRIB3 genes." (PMID 33916466, 2021). "Upregulated ATF4 increases the expression of HSPA5 and activity of glutathione peroxidase 4 (GPX4), thus protecting glioma cells from ferroptosis." (PMID 34163322, 2021). "In this experimental study we investigated the regulation of ATF4, the main orchestrator of the ISR, under conditions of the glioma microenvironment." (PMID 34239013, 2021). "We investigated the effect of TMZ on human glioma cells under conditions of enhanced ATF4 expression (ATF4OE) and ATF4 knock down (ATF4KD)." (PMID 28881638, 2017). "To identify the role of xCT in the ATF4-triggered resistance to TMZ, we evaluated the secretome of glioma cells for extracellular glutamate and cystine levels." (PMID 28881638, 2017). "We also verified these results using qRT-PCR analysis; the mRNA levels of ATF-4, XBP-1 (s), and CHOP obviously increased in U251 and A172 glioma cells in which CERS1 was overexpressed." (PMID 29262618, 2017). "By Western blot, the protein levels of ATF-4, XBP-1 (s), and CHOP increased in U251 and A172 glioma cells in which CERS1 was overexpressed." (PMID 29262618, 2017). "And, the mRNA levels of ATF-4, XBP-1 (s), and CHOP were increased upon C18-ceramide addition in U251 and A172 glioma cells." (PMID 29262618, 2017). "Levels of key UPR transcripts XBP-1, CHOP, ATF4, and ATF6 were only nominally detected in normal brain and unstressed U87 glioma cells, as reported by other studies." (PMID 24039668, 2013). "The protein expression of UPR effectors (ATF4, XBP-1, CHOP/GADD153) is also increased in glioma tumors, indicating that their enhanced transcription indeed leads to increased protein levels." (PMID 24039668, 2013). "We have observed that 2OHOA treatments induced augments in the expression of important ER stress/UPR markers, such as phosphorylated eIF2α, IRE1α, CHOP, ATF4 and the spliced form of XBP1 in human glioma cells." (PMID 23133576, 2012). "We demonstrated that IRT triple treatment of BT16 tumor cells with ONC201, TMZ and RT shows induction of ATF4 indicative of ISR activation, cleaved PARP as a marker of apoptosis, and suppression of RAD51, a selective DNA repair target to radiosensitize glioma stem cells in treated brain tumors." (PMID 40145650, 2025). "Moreover, ATF4 suppression obviously reversed the regulatory role of Sev on protein levels of GPX4, transferrin, and ferritin in glioma cells." (PMID 35372041, 2022). "However, the same drug increased CHOP mRNA and protein expression upon activation of PERK-eIF2α-ATF4 and ATF6 cascade in glioma cells." (PMID 35456680, 2022). "Similarly, we found in this study that GRP78, PERK, and ATF4, as well as ATF3, were all significantly upregulated in the human glioma cells stressed with H2O2 alone." (PMID 34112960, 2021). "Moreover, Western blotting revealed that GRP78, ATF4, and ATF3 were all time-dependently upregulated in the glioma cells treated with 500 μM H2O2 alone." (PMID 34112960, 2021). "Whilst phosphorylated eIF2α, ATF4 and DDIT3 were detected in tryptophan-deprived GL261 cells, phosphorylated GCN2 was not consistently observed in three independent studies with GL261 glioma cells cultured in low tryptophan concentrations." (PMID 30466445, 2018). "Thus, our data demonstrate that ATF4 is involved in the regulation of xCT and this pathway modulates TMZ resistance in gliomas." (PMID 28881638, 2017). "Immunoblot analyses revealed that both human glioma cell lines U87 and U251 show increased ATF4 protein levels compared to non-transformed primary astrocytes." (PMID 28881638, 2017).
glioma (continued). "This is again reflected in immunohistochemistry of glioma xenograft tumors; high levels of CHOP and ATF4 (driven by the PERK arm of the UPR) are evident compared to normal brain, as are those of XBP-1 (where we cannot distinguish between spliced and unspliced versions with this antibody)." (PMID 24039668, 2013). "Western blots analysis was utilized to assess the apoptosis of treated cells and showed induction of ATF4 as marker of ISR activation, cleaved PARP as marker of cell death, and suppression of ATPase Rad51, a selective DNA repair target that radio-sensitizes glioma stem cells in brain tumor cells." (PMID 40145650, 2025). "Moreover, bioinformatics analysis indicated that KPNB1 mRNA expression had moderate negative correlation with that of ATF4 in glioblastoma multiforme but not low grade glioma." (PMID 30742128, 2019). "However, xCT expression was not increased in DHA-treated glioma cells whereas enhanced ATF4 expression was induced." (PMID 31519193, 2019). "Here, we hypothesized that ATF4 inhibition, although not fully lethal for glioma cells, can weaken the cellular resistance mechanisms against TMZ." (PMID 28881638, 2017). "Rat glioma cells revealed a slight but not significant upregulation of ATF4 at 400 μM SAS." (PMID 27074570, 2016). "In the absence of DHA, the basal levels of ROS and MDA in glioma cells are very low and could not be potentiated by knockdown of PERK, ATF4 and HSPA5." (PMID 31519193, 2019).
hepatocellular carcinoma (62 papers, 2010 to 2025). A malignant tumor that arises from hepatocytes. "Current evidence suggests that S-HBsAg activates the FGF19-JAK2-STAT3 pathway through the ATF4 pathway, causing the epithelial-mesenchymal transition of hepatocytes, which can promote the occurrence of hepatocellular carcinoma." (PMID 36535923, 2022). "Furthermore, Gao and colleagues revealed that by inhibiting ferroptosis, YAP/TAZ and ATF4 cause hepatocellular cancer to resist Sorafenib." (PMID 39315094, 2024). "The activation of ATF4 by YAP/TAZ has been shown to shield hepatocellular carcinoma cells from sorafenib-induced ferroptosis." (PMID 40227255, 2025). "For example, regorafenib was shown to promote ferroptosis in hepatocellular carcinoma by upregulating ATF4 and CHOP expression, similar to sorafenib's mechanism of action." (PMID 40688501, 2025). "He and colleagues reported that in non‐alcoholic steatohepatitis (NASH)‐induced Hepatocellular carcinoma (HCC) models, ATF4 deficiency increased susceptibility to ferroptosis via decreasing XCT expression, leading to accelerated development of HCC." (PMID 39836526, 2025). "Stress responses accompany hepatocyte injury, as seen in the ATF4-dependent SLC7A11 expression in a NASH-related hepatocellular carcinoma mouse model." (PMID 38844964, 2024). "A recent study showed that activation of the PERK-eIF2α-ATF4-CHOP pathway is involved in Arnicolide D-induced oncosis in hepatocellular carcinoma cells." (PMID 39144616, 2024). "For example, PERK/ATF4 mediate drug efflux in hepatocellular carcinoma (HCC) via ABC cassette transporter induction." (PMID 39021040, 2024). "We probed these genetic variants for allelic regulatory activity using a massively parallel reporter assay (MPRA) in HepG2 hepatoma cells exposed to tunicamycin to induce endoplasmic reticulum stress and ATF4 upregulation." (PMID 37906604, 2023). "In the present study, we found that metformin promoted ferroptosis and sorafenib sensitivity in hepatocellular carcinoma cells via ATF4/STAT3." (PMID 37326750, 2023). "MiR-214 and miR-3200-5p directly repress ATF4 expression to enhance ferroptosis in hepatocellular carcinoma cells, whereas LncHULC increases ATF4 levels by competing with miR-3200-5p and inhibits ferroptosis." (PMID 37686142, 2023). "Further, in situ, RBBP8 and ATF4 expression levels were analyzed by co-immunostaining in tumor samples from hepatocellular carcinoma patients." (PMID 37591836, 2023). "In conclusion, our study demonstrates that metformin promotes ferroptosis and sorafenib sensitivity in hepatocellular carcinoma cells via ATF4/STAT3." (PMID 37326750, 2023). "Metformin promotes ferroptosis and sensitivity to sorafenib in hepatocellular carcinoma cells via ATF4/STAT3, and it inhibits HCC progression." (PMID 37326750, 2023). "This study was designed to investigate the promotion of ferroptosis and sorafenib sensitivity by metformin in hepatocellular carcinoma cells via ATF4/STAT3." (PMID 37326750, 2023). "In summary, these findings illuminate some of the molecular mechanisms through which downregulation of HULC induces liver cancer cell ferroptosis by targeting the miR-3200-5p/ATF4 axis to modulate the development of hepatocellular carcinoma." (PMID 35615577, 2022). "Dual‐specificity tyrosine (Y) phosphorylation‐regulated kinase (DYRK) 3 reprograms purine synthesis by blocking NCOA3/ATF4 TF complex in hepatocellular carcinoma." (PMID 35092699, 2022). "MiR-214-3p promotes ferroptosis in hepatocellular carcinoma (HCC) by downregulating the expression of activating transcription factor 4 (ATF4)." (PMID 35422492, 2022). "Depletion of ADSL in hepatocellular carcinoma upregulates activating transcription factor 4 (ATF4) and induces mitochondrial stress; however, the effect of SAICAR has not been examined." (PMID 36557247, 2022).
hepatocellular carcinoma (continued). "Our current results elucidate a novel mechanism indicating that downregulation of HULC induces ferroptosis in hepatocellular carcinoma by targeting the miR-3200-5p/ATF4 axis." (PMID 35615577, 2022). "In the current article, we investigate how modulation of the eIF2α–ATF4 stress pathway affects hepatoma cell response to bortezomib." (PMID 34066165, 2021). "Transcriptome profiling revealed that many ATF4 transcriptional target genes are among the most upregulated genes in bortezomib-treated HepG2 human hepatoma cells." (PMID 34066165, 2021). "By using combinations of chemical treatments, we find that eIF2α–ATF4 pathway activity level is a factor affecting hepatoma cell sensitivity to proteasome inhibition." (PMID 34066165, 2021). "The ability of the protein TRIB3 to bind a large portion of genomic sites occupied by ATF4 and restrict ATF4-dependent transcription promotes hepatoma cells resistance to bortezomib treatment." (PMID 34066165, 2021). "The pseudokinase TRIB3, an inhibitor of ATF4, is expressed at a high basal level in hepatoma cells and is strongly upregulated in response to bortezomib." (PMID 34066165, 2021). "In the present article, we characterize the effect of pharmacological modulators of the eIF2α–ATF4 pathway, and of TRIB3, an endogenous inhibitor of ATF4, on the gene expression and viability of HepG2 human hepatoma cells exposed to bortezomib." (PMID 34066165, 2021). "Taken together, the binding of oxysterol to INSIGs elicits activation of PERK in CHO and hepatoma cells, thereby upregulating the eIF2α–ATF4 pathway, followed by induction of cell death." (PMID 34298014, 2021). "As revealed by our experiments with hepatoma cells exposed to bortezomib along with nelfinavir or salubrinal, an overactivation of the eIF2α–ATF4 pathway perturbs other UPR branches and accelerates cell death." (PMID 34066165, 2021). "Hongbiao Huang demonstrated that anacardic acid, a natural compound isolated from the traditional medicine Amphipterygium adstringens, induced hepatoma HepG2 and myeloma U266 tumor cells’ apoptosis via ATF4-dependent ER stress." (PMID 30651744, 2019). "MiR-214 promotes ferroptosis in hepatoma cells by inhibiting ATF4, a potential therapeutic target." (PMID 38840234, 2024). "In diethylnitrosamine-induced hepatocellular carcinoma mouse models, conditional deletion of activating transcription factor 4 (Atf4), an ER stress-related transcription factor, enhances ferroptotic liver damage by downregulating SLC7A11, thus promoting liver tumorigenesis." (PMID 38844964, 2024). "We speculate that metformin affects hepatocellular carcinoma cells sensitivity to sorafenib through the ATF4/STAT3 molecular pathway." (PMID 37326750, 2023). "Therefore, the aim of this study was to investigate the promotion of ferroptosis and sorafenib sensitivity by metformin via ATF4/STAT3 in hepatocellular carcinoma cells." (PMID 37326750, 2023). "To investigate the effects of ETOH on ATF4 in cultured hepatocytes, we used the human hepatoma cell line HepG2, along with the normal mouse hepatocyte cell line AML12, to ensure that the ETOH-induced effects were not unique to the neoplastically transformed phenotype of HepG2 cells." (PMID 37569418, 2023). "Furthermore, while overexpression of ATF4 is sufficient to inhibit ferroptosis in hepatocellular carcinoma cells, ATF4 downregulation activates ferroptosis." (PMID 36815377, 2023). "In addition, it was found that lncRNA HULC plays a role as the ceRNA of miR-3200-5p in hepatocellular carcinoma, and miR-3200-5p can regulate the ferroptosis process by targeting ATF4 and inhibit the proliferation and metastasis of hepatoma cells." (PMID 36408273, 2022). "When looking at single miRNAs, it could be shown that the miRNA 214-3p (miR-214) plays a regulatory role in the hepatocarcinogenesis via the enhancement of erastin-induced ferroptosis and targeting activating transcription factor 4 (ATF4) in hepatoma cells." (PMID 35406596, 2022).
hepatocellular carcinoma (continued). "In hepatocellular carcinoma cells, results from experiments involved with transient transfections of miR-3200-5p suggested that miR-3200-5p could directly bind to ATF4." (PMID 35615577, 2022). "When miR-214-overexpressing Hep3B hepatoma cells were subcutaneously injected into nude mice, it was found that the expression of miR-214 in tumor tissue was increased, while the expression of ATF4 was decreased." (PMID 36408273, 2022). "Since pharmacological perturbation of ATF4 activity affected cell sensitivity to bortezomib, these results raise the possibility that hepatoma cells employ high TRIB3 expression to achieve optimal ATF4 pathway activity and thereby survival under stressful conditions." (PMID 34066165, 2021). "Interestingly, inhibition of GP96 led to a modest increase in ATF4 in hepatoma cells, causing one to ask if the loss of FOXP3 and promotion of IFNγ in GP96 deficient Tregs is due to elevated ATF4." (PMID 30978945, 2019). "While the role of TAZ in modulating ferroptosis is molecular context- and cell type-dependent, a recent study on hepatocellular carcinoma (HCC) reported its implication in preventing ferroptosis in sorafenib-resistant HCC cells through its binding to ATF4." (PMID 40667288, 2025). "The hepatitis B virus (HBV) X protein interacts directly with GRP78, inhibiting eIF2α phosphorylation and subsequently inhibiting ATF4-CHOP-Bcl-2 expression to prevent hepatocellular carcinoma (HCC) cell death and the negative regulation of DNA repair." (PMID 32703221, 2020). "Another study showed that metformin induced ferroptosis and increased sorafenib sensitivity via regulation of ATF4 (activating transcription factor 4) and STAT3 (signal transducer and activator of transcription 3) in hepatocellular carcinoma cells." (PMID 39247188, 2024). "Metformin has been shown to induce iron apoptosis and increase ROS levels in hepatocellular carcinoma cells via ATF4/STAT3, thereby decreasing hepatocellular carcinoma cell resistance to sorafenib." (PMID 38274225, 2023). "The metastatic role of LAMP3 was also further confirmed in head and neck squamous cell carcinoma, oral squamous cell carcinoma (OSCC), and hepatocellular carcinoma (HCC) and has recently been reported as a direct target of ATF4." (PMID 33746610, 2021). "Moreover, in hepatocellular carcinomas (HCC), the induction of PERK/eIF2α/ATF4 signaling following pterostilbene treatment is associated with HCC cell death and reduced tumor growth." (PMID 33842465, 2021). "Using transient transfection and chromatin immunoprecipitation approaches in hepatoma cells, we report the characterization of a functional Amino Acid Response Element (AARE) in the TRB3 promoter and the binding of ATF4, ATF2 and C/EBPβ to this AARE sequence." (PMID 21203563, 2010). "Using transient transfection and chromatin immunoprecipitation approaches in hepatoma cells, we report the characterization of an Amino Acid Response Element (AARE) in the TRB3 promoter and the binding of ATF4, ATF2 and C/EBPβ to this AARE sequence." (PMID 21203563, 2010). "In addition, it has been found that ERS can regulate ATF4 through the PERK pathway to promote autophagy and inhibit cell death in hepatocellular carcinoma cells." (PMID 36535923, 2022). "Knockout of INSIG1 or INSIG2 in human hepatoma Huh7 cells attenuated ATF4 protein upregulation, indicating that only one of the endogenous INSIGs, unlike overexpression of intrinsic INSIG1 or INSIG2, was insufficient for ATF4 induction." (PMID 34298014, 2021). "In one direction, ATF4 transcriptionally induces several stress-responsive lncRNAs such as GOLGA2P10 and linc01564, which contribute to hepatocellular carcinoma (HCC) survival and metabolic reprogramming." (PMID 40777108, 2025). "Hence, multiple ATF4 target genes are co-bound by TRIB3 and might participate in the regulation of cell death in response to bortezomib treatment in hepatocellular carcinoma cells." (PMID 34066165, 2021).
hepatocellular carcinoma (continued). "Among hepatoma cell lines, cell viability data from both drug screening projects revealed a positive correlation between resistance to bortezomib and the expression level of TRIB3, a gene upregulated by bortezomib and known to be a negative regulator of the ATF4 pathway." (PMID 34066165, 2021). "Dihydroartemisinin (DHA) induces ferroptosis in hepatocellular carcinoma (HCC) by inhibiting ATF4, thus decreasing SLC7A11 expression and enhancing lipid peroxidation, also improving chemosensitivity to sorafenib, offering a novel therapeutic approach for HCC." (PMID 39315094, 2024).